LOXL1 (lysyl oxidase like 1)
Description:
Catalyzes the oxidative deamination of lysine and hydroxylysine residues in collagen and elastin, resulting in the formation of covalent cross-linkages, and the stabilization of collagen and elastin fibers (By similarity). Essential for the elastic fiber homeostasis and for their maintenance at adult age (By similarity).
Synonyms: LOL; LOXL
Tractability: Antibody: UniProt places it where antibodies can reach, with high confidence; its Gene Ontology location is reachable by antibodies, with high confidence; UniProt predicts a signal peptide or a membrane-spanning region. PROTAC: a small molecule that binds it is known.
Target class: Enzyme; Oxidoreductase
Gene: Protein-coding gene on chromosome 15 (73,925,989 to 73,952,137, forward strand). Ensembl gene ENSG00000129038.
Subcellular location: Secreted, extracellular space; Secreted, extracellular space, extracellular matrix
Subcellular location (Human Protein Atlas): Endoplasmic reticulum; Predicted to be secreted
Pathways (Reactome):
Extracellular matrix organization: Crosslinking of collagen fibrils; Elastic fibre formation
Gene Ontology:
Molecular function: protein binding; protein-lysine 6-oxidase activity; copper ion binding; oxidoreductase activity, acting on the CH-NH2 group of donors, oxygen as acceptor
Biological process: collagen fibril organization; protein deamination; aorta development; response to lipopolysaccharide
Cellular component: extracellular matrix; extracellular region; elastic fiber; acrosomal vesicle; basement membrane
Genetic constraint (gnomAD): Loss-of-function variants: 25 observed, 32.78 expected, observed/expected ratio (o/e) 0.76, 90% interval 0.56 to 1.07. The synonymous counts are far from expectation, so gnomAD's model fits this gene poorly and the ratio says little. Missense variants: 660 observed, 577.79 expected, observed/expected ratio (o/e) 1.14, 90% interval 1.07 to 1.22. Synonymous variants: 333 observed, 260.68 expected, observed/expected ratio (o/e) 1.28, 90% interval 1.17 to 1.4.
Homologues: Orthologues: chimpanzee LOXL1 (99% identical), macaque LOXL1 (98% identical), pig LOXL1 (93% identical), mouse Loxl1 (92% identical), rat Loxl1 (91% identical), guinea pig LOXL1 (87% identical), rabbit LOXL1 (81% identical), dog LOXL1 (70% identical), zebrafish loxl1 (55% identical). Paralogues in human: LOX (37% identical), LOXL3 (28% identical), LOXL4 (27% identical), LOXL2 (27% identical), DMBT1 (13% identical), CD163L1 (12% identical), CD163 (12% identical), PRSS12 (12% identical), SSC5D (11% identical), SCART1 (11% identical), SSC4D (10% identical), CD6 (9% identical), and 3 more.
Diseases named in the same sentence as LOXL1 in open-access papers:
LOXL1 is named in the same sentence as 121 diseases in open-access papers, as found by Europe PMC text mining. Sharing a sentence is not in itself a finding about the gene and the disease. The quoted sentences say what the papers report.
exfoliation syndrome (74 papers, 2008 to 2025). An autosomal dominant disorder caused by mutations in the LOXL1 gene, encoding lysyl oxidase homolog 1. "LOXL3 is of special interest given that LOXL1, a related lysyl oxidase, is the well-known genetic risk factor for exfoliation syndrome and XFG, with a single polymorphism accounting for the majority of cases." (PMID 41042282, 2025). "The outcomes of trabeculectomy for exfoliation glaucoma are inferior to those for POAG in Asian patients, and the LOXL1 gene variant associated with exfoliation glaucoma differs between Asians and Caucasians." (PMID 39458082, 2024). "LOXL1 (lysyl oxidase like 1), which is implicated in pseudoexfoliation syndrome, was highly expressed in equatorial lens epithelium." (PMID 37138096, 2023). "On the basis of our previously reported work, the association of lysyl oxidase-like 1 (LOXL1) promoter region gene polymorphism with exfoliation syndrome (XFS) and exfoliation glaucoma (XFG) in Uygur individuals was examined." (PMID 35942063, 2022). "In Pseudoexfoliation Glaucoma, the deficiency of Loxl1 is associated with decreased elastin incorporation into elastic lamina of blood vessels, resulting in released soluble elastin and leakage of serum proteins, inflammatory cytokines into aqueous humor." (PMID 34923484, 2021). "The present article studied the association between three single nucleotide polymorphisms (SNPs) in the LOXL1 gene and the presence of exfoliation glaucoma in Southwestern Sweden." (PMID 34573365, 2021). "The present study aimed at investigating the association between three single nucleotide polymorphisms (SNPs) in the LOXL1 gene and the presence of exfoliation glaucoma in patients living in Southwestern Sweden." (PMID 34573365, 2021). "The LOXL1 variant is mostly considered a risk factor in the development of exfoliation syndrome and glaucoma." (PMID 34440405, 2021). "As a result, we found one association with the LOXL1 gene variant which is known for its role in exfoliation syndrome (XFS) manifestation and glaucoma." (PMID 34440405, 2021). "Single nucleotide polymorphisms (SNPs) in the gene encoding LOXL1 are risk factors for exfoliation syndrome and exfoliation glaucoma." (PMID 33909695, 2021). "This meta-analysis comprehensively investigated the association between LOXL1 gene polymorphisms (rs1048661, rs3825942, and rs2165241) and the risk of exfoliation syndrome/exfoliation glaucoma (XFS)/(XFG)." (PMID 33909695, 2021). "A study conducted in 2010 explored the relationship of single nucleotide polymorphisms (SNPs) with the lysyl oxidase-like 1 (LOXL1) gene with pseudoexfoliation glaucoma (PEG) using LOXL1 coding region sequencing techniques." (PMID 32630516, 2020). "LOXL1 gene is the most important genetic risk factor known so far for pseudoexfoliation glaucoma (XFG)." (PMID 26319397, 2015). "The present knowledge on the association of single nucleotide polymorphisms (SNPs) of lysyl oxidase-like 1 (LOXL1) with pseudoexfoliation syndrome (PEXS) and pseudoexfoliation glaucoma (PEXG) is controversial and inconclusive." (PMID 24603551, 2014). "A genome-wide association study identified three common single nucleotide polymorphisms (SNPs) in the LOXL1 gene on chromosome 15q24.1 that were strongly associated with pseudoexfoliation syndrome." (PMID 24603551, 2014). "Exfoliation syndrome, a condition predisposing to elevated intraocular pressure, is associated with genetic variants in LOXL1, however, these variants appear to contribute to the development of the exfoliation syndrome and not to optic nerve disease in POAG." (PMID 22570617, 2012). "This study is the first study of LOXL1 copy number variants in exfoliation glaucoma conducted in black South African subjects." (PMID 23288989, 2012). "Sequence tags from 2 recently identified glaucoma-related genes, lysyl oxidase 1 (LOXL1; associated with exfoliation glaucoma), and caveolin 1 and caveolin 2 (associated with POAG) were expressed in at least two libraries." (PMID 21528004, 2011).
exfoliation syndrome (continued). "A particularly interesting example is that of the LOXL1 polymorphisms rs3825942 and rs1048661, which are in linkage disequilibrium and both show association with exfoliative glaucoma (XFG)." (PMID 21067572, 2010). "An example is seen in the LOXL1 locus where two nonsynonymous SNPs, thought to be pathogenic variants, account for an association with exfoliation glaucoma." (PMID 20661439, 2010). "The results of this study suggest a causative functional relationship between LOXL1 expression and pseudoexfoliation glaucoma." (PMID 21139690, 2010). "Another example is exfoliation syndrome and LOXL1 where the risk allele of rs1048661 is inverted between Icelandic (allele G) and Japanese (allele T) populations." (PMID 19779542, 2009). "Recent genetic studies in multiple populations have convincingly identified the lysyl oxidase-like 1 (LOXL1) gene as a significant contributor to the genetic risk of developing pseudoexfoliation syndrome." (PMID 18806885, 2008). "We performed genetic association studies using a native Japanese population to examine the reproducibility of results of lysyl oxidase-like 1 (LOXL1) genetic association studies for exfoliation glaucoma (XFG) beyond the differences of ethnicity." (PMID 18552979, 2008). "The lysyl oxidase-like protein 1 (LOXL1) gene is strongly associated with exfoliation glaucoma, which is very rare in the Chinese population." (PMID 19098994, 2008). "A common haplotype of the LOXL1 gene has recently been shown to be a major genetic factor associated with pseudoexfoliation syndrome." (PMID 18806885, 2008). "In summary, we have demonstrated significant associations of LOXL1 variants with Japanese patients who have exfoliation syndrome/glaucoma." (PMID 18958304, 2008). "In this study, we evaluated the association of three LOXL1 SNPs in Japanese patients with exfoliation syndrome/glaucoma, primary open angle glaucoma, normal tension glaucoma, and cataract." (PMID 18958304, 2008). "Age and the LOXL1 diplotype were significantly associated with pseudoexfoliation syndrome as previously reported (p<0.001)." (PMID 18806885, 2008). "In the Icelandic and Swedish populations, pseudoexfoliation syndrome (XFS) and pseudoexfoliation glaucoma (XFG) has been significantly associated with LOXL1 exon 1 polymorphisms - allele G of rs1048661 (R141L) and allele G of rs3825942 (G135D)." (PMID 18334947, 2008). "Estimated two- and three-loci haplotype frequencies for three LOXL1 SNPs and their corresponding association tests between exfoliation syndrome and controls." (PMID 18385788, 2008). "Additional genetic or environmental risk factors other than LOXL1 are likely to be associated with an increase in exfoliation glaucoma among exfoliation syndrome patients." (PMID 18958304, 2008). "Genotypic and allelic counts, frequencies, and p-values for three LOXL1 polymorphisms in different subtypes of exfoliation syndrome." (PMID 18385788, 2008). "It is currently unclear whether the deposits observed with iPSC-derived LEPC are associated with changes in LOXL1 function as has been suggested for pseudoexfoliation syndrome." (PMID 36497012, 2022). "Interestingly, pseudoexfoliation syndrome was associated with Loxl1 gene function, and it has been recently shown that PEDF expression level was also correlated with pseudoexfoliation." (PMID 35174090, 2022). "Although there is a confirmed genetic association of LOXL1 to pseudoexfoliation syndrome and open-angle glaucoma, it is still unclear the role that LOXL proteins may play in the cornea." (PMID 34746916, 2021). "This cross-sectional study investigated possible association between LOXL1 gene polymorphisms and exfoliative glaucoma in Northeastern part of Iran between May 2014 and May 2015." (PMID 31850260, 2019). "Such “flip-flop” associations may be due to population-specific effects, which have been well documented in genetic association studies such as the association of LOXL1 with exfoliation syndrome." (PMID 27272641, 2016).
exfoliation syndrome (continued). "In contrast to POAG, a single locus on the LOXL1 gene significantly contributes to elevated risk for developing exfoliation syndrome, a condition that is highly prevalent in some populations and may lead to secondary glaucoma." (PMID 23536807, 2013). "LOXL1, a gene recently linked to pseudoexfoliation glaucoma was altered only by the Q368X mutation." (PMID 22615763, 2012). "Interestingly, another member of this gene family lysyl oxidase-like 1 (LOXL1) has been found to contain two single nucleotide polymorphisms (SNPs) in patients who develop pseudoexfoliation glaucoma." (PMID 19145252, 2009). "CA patients of Scandinavian ancestry with pseudoexfoliation glaucoma exhibit variations in the LOXL1 gene sequence that may predispose this group to elevated IOP and glaucomatous optic neuropathy due to accumulation of pseudoexfoliation material." (PMID 18716680, 2008). "Additional genetic or environmental risk factors other than these LOXL1 SNPs could be associated with the development of exfoliation syndrome as well as exfoliation glaucoma among exfoliation syndrome patients." (PMID 18958304, 2008). "The association with pseudoexfoliation was not different between patients with only the pseudoexofoliation syndrome compared with patients with pseudoexfoliation glaucoma, arguing that the LOXL1 protein participates in the syndrome and in the associated glaucoma." (PMID 18254956, 2008). "Using a U.S. clinic-based case control sample with broad ethnic diversity, we show that three common SNPs in LOXL1 previously associated with pseudoexfoliation in Nordic populations are significantly associated with pseudoexfoliation syndrome and pseudoexfoliation glaucoma." (PMID 18254956, 2008). "Based on this study among 393 elderly Japanese patients with exfoliation syndrome, exfoliation glaucoma, primary open-angle glaucoma, and cataract, we confirmed the findings of Thorleifsson and colleagues that three SNPs within LOXL1 are strongly associated with exfoliation syndrome and glaucoma." (PMID 18958304, 2008). "The LOXL1 association of exfoliation glaucoma is through the association of exfoliation syndrome." (PMID 18958304, 2008). "As LOXL1 is known to contribute a significant proportion of the genetic risk of pseudoexfoliation syndrome, it is possible that another genetic modifier locus could have only minor relative risks." (PMID 18806885, 2008). "Taken together, the data suggest that besides the LOXL1 risk alleles, other genetic variants or environmental factors may contribute to the risk of developing pseudoexfoliation syndrome." (PMID 18806885, 2008). "Accordingly, the inclusion criteria of the control group might contribute to the extremely significant association of the LOXL1 SNPs with exfoliation syndrome in this study." (PMID 18958304, 2008). "However, association analysis helped us to identify the genomic variant rs3825942 in the gene LOXL1 that may be protective against a specific eye disease, exfoliation syndrome." (PMID 34440405, 2021). "The purpose of this study was to evaluate association profiles of lysyl oxidase-like 1 (LOXL1) gene polymorphisms with pseudoexfoliation syndrome (XFS) in a Korean population." (PMID 23441117, 2013). "Two coding single nucleotide polymorphisms (SNPs) in lysyl oxidase-like 1 (LOXL1) are major genetic risk factors for pseudoexfoliation syndrome (XFS) and pseudoexfoliation glaucoma (XFG) in diverse populations." (PMID 24068861, 2013). "In vitro cultures of human Tenon capsule fibroblasts obtained from patients with pseudoexfoliation syndrome indicated that the increased expression of elastin is related to the level of LOXL1 (Bernstein, Ritch & Wolosin, 2018)." (PMID 40786111, 2025). "Lysyl Oxidase Like 1 (LOXL1) has been described in previous studies as a predictor factor for exfoliation glaucoma." (PMID 34573365, 2021).
exfoliation syndrome (continued). "For example, a large-scale GWAS study found that LOXL1 variants can increase the deposition of elastin and fibrillin-1 that stabilizes the ECM, thereby protecting against exfoliation syndrome." (PMID 34393991, 2021). "LOXL1-AS1 is a lncRNA encoded on the opposite strand of lysyl oxidase-like 1 (LOXL1), which was found to strongly associated with exfoliation glaucoma and exfoliation syndrome." (PMID 30944201, 2019). "Increased levels of LOXL1 are involved in the formation of abnormal fiber aggregates in exfoliation glaucoma or PEX." (PMID 30673862, 2019). "The lysyl oxidase-like 1 (LOXL1) gene, identified as a genetic risk factor for exfoliation glaucoma or PEX is a cross-linking enzyme involved in extracellular matrix metabolism." (PMID 30673862, 2019). "Our previous data suggested that three single-nucleotide polymorphisms (SNPs), rs1048661, rs3825942, and rs2165241, of the lysyl oxidase-like 1 gene (LOXL1) are significantly associated with exfoliation syndrome (XFS) and exfoliation glaucoma (XFG)." (PMID 31192002, 2019). "Two single nucleotide polymorphisms in the lysyl oxidase-like 1 (LOXL1) gene (rs1048661 and rs3825942) have recently been identified as strong genetic risk factors for pseudoexfoliative glaucoma." (PMID 27895937, 2016). "Previous data on adipose tissues have shown that the expression of LOXL1 is decreased by 7.7% per risk allele of SNP rs1048661 (R141L) in PEXS and pseudoexfoliation glaucoma." (PMID 24739284, 2014). "A significant association between common single nucleotide polymorphisms (SNPs) in the lysyl oxidase-like 1 (LOXL1) gene on chromosome 15q24.1 with PEX and pseudoexfoliation glaucoma (PEXG) in populations of different ethnicity was recently established." (PMID 23869164, 2013). "Three common sequence variants in the lysyl oxidase-like 1 (LOXL1) gene were recently associated with pseudoexfoliation (PEX) and pseudoexfoliation glaucoma (PEXG) in populations from various parts of the world." (PMID 23869164, 2013). "Further work is also required to elucidate which genetic factors in addition to LOXL1 are responsible for pseudoexfoliation syndrome." (PMID 18806885, 2008). "LOXL1 allelic frequencies of rs1048661 and rs3825942 in Japanese patients with exfoliation syndrome and controls." (PMID 18648524, 2008). "Comparison of allelic counts and the corresponding p-values for LOXL1 SNP markers of rs1048661,rs3825942, and rs2165241 and different subtypes of exfoliation syndrome." (PMID 18385788, 2008). "Further research into the role of the LOXL1 protein in the etiology of exfoliation syndrome and exfoliation glaucoma is urgently needed." (PMID 18385788, 2008). "No direct causal link has been established between LOXL1 variants in pseudoexfoliation syndrome and PDS/PG, necessitating further research." (PMID 38397132, 2024). "The most frequently studied gene related to exfoliation syndrome is Lysyl Oxidase Like 1 (LOXL1)." (PMID 34573365, 2021). "The lack of association between LOXL1 and primary glaucoma has provided evidence supporting that LOXL1 is linked to the pathogenesis of the exfoliation syndrome but not the direct genetic cause of IOP elevation and subsequent glaucoma." (PMID 20142848, 2010). "List of coding variants identified from LOXL1 exon sequencing in South African black individuals with or without exfoliation glaucoma." (PMID 20431720, 2010). "Frequencies of LOXL1 haplotypes in patients with exfoliation glaucoma and control subjects." (PMID 18483563, 2008). "Until now, several lines of studies have reported significant associations of these LOXL1 SNPs with exfoliation syndrome or the lack of associations of these SNPs with primary open-angle glaucoma in various populations." (PMID 18958304, 2008). "LOXL1 haplotypes in patients with exfoliation syndrome and in controls." (PMID 18648524, 2008).